DHRS4L2 (dehydrogenase/reductase 4 like 2)
Description:
Probable oxidoreductase.
Synonyms: SDR25C3
Tractability: Antibody: UniProt places it where antibodies can reach, with high confidence; UniProt predicts a signal peptide or a membrane-spanning region; its Gene Ontology location is reachable by antibodies, with medium confidence. PROTAC: ubiquitination databases record sites on it.
Gene: Protein-coding gene on chromosome 14 (23,969,874 to 24,006,408, forward strand). Ensembl gene ENSG00000187630.
Subcellular location: Secreted
Gene Ontology:
Molecular function: carbonyl reductase (NADPH) activity
Biological process: retinal metabolic process
Cellular component: mitochondrion; peroxisome; extracellular region
Genetic constraint (gnomAD): Loss-of-function variants: 22 observed, 24.06 expected, observed/expected ratio (o/e) 0.91, 90% interval 0.65 to 1.31. The upper end of that interval is the gene's LOEUF score, 1.31, which puts it in group 5 of 6, group 1 being the genes least tolerant of losing a copy. Missense variants: 385 observed, 293.25 expected, observed/expected ratio (o/e) 1.31, 90% interval 1.21 to 1.43. Synonymous variants: 141 observed, 122.12 expected, observed/expected ratio (o/e) 1.15, 90% interval 1.01 to 1.33.
Homologues: Orthologues: dog DHRS4 (76% identical), guinea pig DHRS4 (75% identical), rabbit DHRS4 (75% identical), mouse Dhrs4 (73% identical), pig DHRS4 (72% identical), rat Dhrs4 (72% identical), zebrafish zgc:101858 (23% identical), Drosophila melanogaster CG3699 (22% identical), tropical clawed frog MGC79752 (22% identical), Caenorhabditis elegans Y47G6A.22 (22% identical), Drosophila melanogaster CG12171 (21% identical), Drosophila melanogaster CG31549 (21% identical), and 18 more. Paralogues in human: DHRS4 (87% identical), DHRS2 (57% identical), RDH8 (24% identical), HSD11B1 (23% identical), DHRS7 (23% identical), CBR1 (22% identical), CBR3 (21% identical), DHRS7B (21% identical), DHRS7C (20% identical), HSD11B1L (20% identical), DHRS11 (19% identical), DHRS1 (16% identical), and 1 more.
Diseases named in the same sentence as DHRS4L2 in open-access papers:
DHRS4L2 is named in the same sentence as 5 diseases in open-access papers, as found by Europe PMC text mining. Sharing a sentence is not in itself a finding about the gene and the disease. The quoted sentences say what the papers report.
neuroblastoma (1 paper, 2019). Neuroblastoma (NB) is the most common solid, extracranial childhood tumor. "DHRS4L2 is a member of the dehydrogenase reductase family, with specific alternative transcripts expressed in neuroblastoma." (PMID 31729991, 2019).
cancer (2 papers, 2016 to 2020). A tumor composed of atypical neoplastic, often pleomorphic cells that invade other tissues. "CHRNB4 was also associated with long noncoding RNA, such as DHRS4-AS1, DHRS4L2, DHRS4L1, and SMAD5-AS1, which functions by affecting the proliferation, invasion (epithelial-mesenchymal transition), cell cycle progression and the apoptosis of cancer cells." (PMID 33304845, 2020).
DHRS4L2 also shares sentences with these, for which no sentence is quoted: leukemia (1 paper); mucinous tumors (1); tumor (1).